ADH7 (alcohol dehydrogenase 7 (class IV), mu or sigma polypeptide)
Description:
Catalyzes the NAD-dependent oxidation of all-trans-retinol, alcohol, and omega-hydroxy fatty acids and their derivatives. Oxidizes preferentially all trans-retinol, all-trans-4-hydroxyretinol, 9-cis-retinol, 2-hexenol, and long chain omega-hydroxy fatty acids such as juniperic acid. In vitro can also catalyze the NADH-dependent reduction of all-trans-retinal and aldehydes and their derivatives. Reduces preferentially all trans-retinal, all-trans-4-oxoretinal and hexanal. Catalyzes in the oxidative direction with higher efficiency. Therefore may participate in retinoid metabolism, fatty acid omega-oxidation, and elimination of cytotoxic aldehydes produced by lipid peroxidation.
Synonyms: ADH-4
Tractability: Small molecule: an approved drug acts on it; a structure with a bound ligand is known; it has a high-quality binding pocket; it belongs to a druggable protein family. Antibody: its Gene Ontology location is reachable by antibodies, with high confidence. PROTAC: a small molecule that binds it is known.
Target class: Enzyme; Oxidoreductase
Safety:
Unwanted effects reported when the protein is acted on. In parentheses: how it was acted on, where the effect was seen, and who reports it.
cardiotoxicity (source: ClinPGx)
Gene: Protein-coding gene on chromosome 4 (99,412,261 to 99,435,510, reverse strand). Ensembl gene ENSG00000196344.
Subcellular location: Cytoplasm
Subcellular location (Human Protein Atlas): Cytosol; Plasma membrane
Pathways (Reactome):
Metabolism: Ethanol oxidation; Fatty acids
Gene Ontology:
Molecular function: alcohol dehydrogenase (NAD+) activity; aldehyde oxidase activity; all-trans-retinol dehydrogenase (NAD+) activity; ethanol binding; omega-hydroxydecanoate dehydrogenase activity; receptor antagonist activity; retinol binding; zinc ion binding; oxidoreductase activity
Biological process: fatty acid omega-oxidation; response to bacterium; response to ethanol; retinoid metabolic process; retinoic acid metabolic process; retinol metabolic process; monocarboxylic acid metabolic process
Cellular component: cytosol; cytoplasm
Genetic constraint (gnomAD): Loss-of-function variants: 39 observed, 35.65 expected, observed/expected ratio (o/e) 1.09, 90% interval 0.85 to 1.43. The upper end of that interval is the gene's LOEUF score, 1.43, which puts it in group 5 of 6, group 1 being the genes least tolerant of losing a copy. Missense variants: 538 observed, 481.85 expected, observed/expected ratio (o/e) 1.12, 90% interval 1.04 to 1.2. Synonymous variants: 180 observed, 170 expected, observed/expected ratio (o/e) 1.06, 90% interval 0.94 to 1.2.
Homologues: Orthologues: chimpanzee ADH7 (98% identical), pig ADH7 (92% identical), mouse Adh7 (89% identical), rat Adh7 (87% identical), zebrafish zgc:77938 (53% identical), zebrafish adh5l (52% identical), zebrafish adh8a (52% identical), zebrafish adh8b (50% identical), Caenorhabditis elegans D2063.1 (21% identical), Caenorhabditis elegans adh-1 (20% identical), Caenorhabditis elegans sodh-2 (20% identical), Caenorhabditis elegans ZK829.7 (17% identical), and 1 more. Paralogues in human: ADH1B (69% identical), ADH1C (69% identical), ADH1A (69% identical), ADH5 (60% identical), ADH6 (60% identical), ADH4 (58% identical), RTN4IP1 (19% identical), SORD (19% identical), CRYZ (19% identical), TP53I3 (18% identical), MECR (17% identical), VAT1 (17% identical), and 5 more.
Diseases named in the same sentence as ADH7 in open-access papers:
ADH7 is named in the same sentence as 33 diseases in open-access papers, as found by Europe PMC text mining. Sharing a sentence is not in itself a finding about the gene and the disease. The quoted sentences say what the papers report.
gastric cancer (3 papers, 2021 to 2024). A primary or metastatic malignant neoplasm involving the stomach. "Besides their involvement in metabolizing exogenous substances through cytochrome P450 and drug metabolic pathways, ADH7, ALDH3A1, and ADH1B are also cross-genes with high connectivity within these pathways, indicating their potential use as diagnostic and prognostic biomarkers for gastric cancer." (PMID 39418180, 2024). "It was confirmed that ADH7, CWH43 and SCNN1B all showed low expression in gastric cancer cells (p < 0.05)." (PMID 37359529, 2023). "In this study, three biomarkers, ADH7, CWH43 and SCNN1B, were included in the model that used multiple bioinformatics methods to screen for gastric cancer." (PMID 37359529, 2023).
squamous cell carcinoma (3 papers, 2021 to 2024). A carcinoma arising from squamous epithelial cells. "ADH7 showed promise as a prognostic biomarker and chemotherapy target for gastric adenocarcinoma, with low ADH7 expression and is related to the prognosis of patients with better histological types of adenocarcinoma and squamous cell carcinoma." (PMID 35845594, 2022).
alcohol dependence (2 papers, 2012 to 2014). Physical and psychological dependence on alcohol. "The results of the present study suggest that a variant (rs991316) located downstream of the alcohol dehydrogenase 7 gene (ADH7) may play a role in protection from alcohol dependence in this Mexican American cohort." (PMID 25527893, 2014). "A protective variant (rs991316) located downstream from the ADH7 (alcohol dehydrogenase 7) gene showed suggestive significance in association with alcohol dependence symptom counts derived from DSM-III-R and DSM-IV criteria, as well as to clustered alcohol dependence symptoms." (PMID 25527893, 2014). "The ADH7 gene has been shown to have a protective role against alcohol dependence in previous studies involving other ethnicities, but to our knowledge, has not been reported for Mexican Americans." (PMID 25527893, 2014). "Previous studies have shown that interactions between SNPs across these genes are apparent in the risk of alcoholism, in particular between ADH1B and ADH7 and between ADH4 and ADH1A." (PMID 23166662, 2012). "Because this particular variant near ADH7 (rs991316) had not been previously reported to be associated with alcohol dependence, we wanted to rule out the possibility that this effect was simply the result of LD with a variant in one of the other ADH genes." (PMID 25527893, 2014). "Additionally, this ADH7 SNP (rs991316) has not been identified to be significantly associated with alcohol dependence." (PMID 25527893, 2014). "ADH7 has been shown to have a protective role against alcohol dependence in previous studies involving other ethnicities, but has not been reported for Mexican Americans." (PMID 25527893, 2014).
cervical cancer (2 papers, 2020 to 2024). A primary or metastatic malignant neoplasm involving the cervix. "Recent research showed that alcohol dehydrogenase 7 (ADH7), which was enriched in the retinoic acid metabolic process and the retinol metabolism pathway, played pivotal roles in the progression of cervical cancer and was significantly associated with cervical cancer survival rate." (PMID 39450338, 2024). "The aberrant expression of many mRNAs, including FGFR3, CTGF, TP63, IL36G, ADH7, SPINK5, and so on, have also been identified in cervical cancer." (PMID 32123519, 2020).
acne (1 paper, 2021). An inflammatory process of the sebaceous glands which is characterized by comedones, nodules, papules and/or pustules on the skin. "Recently, ADH7 rs1154469 has been identified as a novel susceptibility locus for severe acne among Han Chinese." (PMID 33849530, 2021). "In addition, the following variants were significantly associated with acne risk: ADH7 (alcohol dehydrogenase 7) rs1154469, SRD5A2 (steroid 5 alpha-reductase 2) TA repeat VNTR and VDR (vitamin D receptor) rs731236 and rs7975232." (PMID 33849530, 2021).
aniridia (1 paper, 2025). Aniridia is a congenital ocular malformation characterized by the complete or partial absence of the iris. "In congenital aniridia, with PAX6 haploinsufficiency, we could observe deregulated expression of the retinoic acid signaling components ADH7 and ADH1A1 in previous studies." (PMID 40094891, 2025).
Barrett esophagus (1 paper, 2021). Esophageal lesion lined with columnar metaplastic epithelium which is flat or villiform. "Similarly to ADH7, it has been associated to Barrett's esophagus, a premalignant precursor of esophageal adenocarcinoma." (PMID 33664777, 2021).
diabetes (1 paper, 2010). "The relationship of this ALDH2 variant as well as the ADH7 and ALDH1b1 variants with diabetes and CHD related phenotypes have not been studied previously, except from a previous study (n = 1,216) from our group." (PMID 20700531, 2010).
glioblastoma (1 paper, 2022). The most malignant astrocytic tumor (WHO grade IV). "To test this prediction, we used a dual-guide CRISPR/enCas12a vector (see “Methods”) to knock out either CPD or negative control ADH7 in glioblastoma cell lines and examined MET protein." (PMID 35768873, 2022).
head and neck cancer (1 paper, 2023). A primary or metastatic malignant neoplasm affecting the head and neck. "In the current study, ADH7 rs1154460G>A SNP was associated with an increased risk of head and neck cancer." (PMID 37510768, 2023). "They reported that the OR of the GG genotype in ADH7 rs1573496C>G was 0.32 (95% CI: 0.13–0.82), and the OR of CG+GG genotype was 0.74 (95% CI: 0.59–0.94), indicating a decreased risk of head and neck cancer." (PMID 37510768, 2023). "Only a few studies exist on the association between ADH7 SNPs and the risk of head and neck cancer." (PMID 37510768, 2023). "In addition, in the current study, ADH7 rs3737482T>C SNP was associated with decreased risk of head and neck cancer." (PMID 37510768, 2023). "In addition, another study conducted in Japan using 585 patients with head and neck cancer and 1170 controls reported that ADH7 rs1573496 SNP was comprised of all homozygous C alleles, and further analysis was not possible." (PMID 37510768, 2023). "In terms of ADH7 SNPs in head and neck cancer, ADH7 rs1573496 SNP has been most commonly investigated." (PMID 37510768, 2023). "In addition, there has been no study on ADH7 SNPs of head and neck cancer in South Korea." (PMID 37510768, 2023).
laryngeal squamous cell carcinoma (1 paper, 2020). A squamous cell carcinoma that arises from the larynx. "In a gene expression study on laryngeal squamous cell carcinoma, a subtype of HNSCC, ADH1C, and ADH7 showed a tumor stage-dependent decreasing expression pattern." (PMID 31940827, 2020).
lipid metabolism disorders (1 paper, 2023). "Mechanistically, loss of Mettl3 significantly downregulated the expression levels of multiple m6A-modified mRNAs related to lipid metabolism, including Adh7, Cpt1a, and Cyp7a1, further promoting lipid metabolism disorders and liver injury in mice." (PMID 37335109, 2023).
nasal polyps (1 paper, 2017). "The PPIA enzyme has been implicated in a wide range of inflammatory and apoptosis pathways, while ADH7 is a hormone that participates in cellular differentiation and could play a crucial role in formation of nasal polyps." (PMID 29270391, 2017).
nicotine dependence (1 paper, 2014). Physical and psychological dependence on nicotine. "We found that the variants in alcohol dehydrogenase genes- rs1229984 (ADH1B), rs698 (ADH1C) and rs1573496 (ADH7) and the nicotine dependence gene variant rs16969968 were less common among Indians compared to previous studies in predominantly western populations." (PMID 24505444, 2014). "We investigated six variants known to influence nicotine addiction or alcohol metabolism, including rs16969968 (CHRNA5), rs578776 (CHRNA3), rs1229984 (ADH1B), rs698 (ADH1C), rs1573496 (ADH7), and rs4767364 (ALDH2)." (PMID 24505444, 2014).
oral cancer (1 paper, 2023). "Also, the other study conducted in India to evaluate the relationship between oral cancer and alcohol metabolism revealed the rarity of ADH7 rs1573496 in the Indian population." (PMID 37510768, 2023).
ovarian carcinoma (1 paper, 2022). A malignant neoplasm originating from the surface ovarian epithelium. "Unlike miR-223, data concerning the role of miR-3065 in cancer have been relatively limited; however, miR-3065 was recently found to be a potential predictor of disease severity in ovarian cancer, along with its target ADH7." (PMID 35163585, 2022).
cancer (10 papers, 2012 to 2023). A tumor composed of atypical neoplastic, often pleomorphic cells that invade other tissues. "SNPs in this region (i.e. rs1229984 [ADH1B], rs1789924 [ADH1C] and rs971074 [ADH7]) have previously been associated with overall UADT cancer." (PMID 22662130, 2012). "In addition, single nucleotide polymorphisms in ADH7 are susceptibility factors for cancer and drug dependence." (PMID 37359529, 2023). "Studies indicate that this gene is activated constitutively in malignant tumors and the action of some molecules with anti-tumor activity is attributed to the inactivation of this factor; a group of genes encoding alcohol dehydrogenases (Adh1, Adh5, Adh6a, Adh6b, Adh7) maps at 138 Mb." (PMID 34966170, 2022). "Moreover, we noticed that three upregulated genes in the high-risk group, ALDH3A1, ALDH3B2, and ADH7, participate in the cytochrome P450-mediated metabolism of trichloroethylene; trichloroethylene is an organic chemical, exposure to which can cause cancer." (PMID 32858528, 2020). "They reported that the CC genotype of ADH7 rs1573496C>G exhibits an OR of 0.68 (95% CI: 0.60–0.78), showing a protective effect against cancer." (PMID 37510768, 2023). "On the other hand, the hypermethylation of ADHFE1 further reduced the expression of neighbouring proteins, ADH6, ADH7, as well as ADH1A, in which the genes were associated with the patient’s prognosis and cancer pathogenesis." (PMID 35054365, 2022).
tumor (8 papers, 2014 to 2025). "ADH7, involved in retinol metabolism, has been reported to have tumor-suppressive functions, and its dysregulation is implicated in gastric epithelial transformation." (PMID 40725485, 2025). "ADH7, implicated in tumor progression by modulating the retinoic acid metabolic process, could predict favorable outcomes for CC." (PMID 38672263, 2024). "Single-cell localization analysis of the risk genes demonstrated that only ADH7, SFN, WWC1, PAK6, and TEAD3 were detectable in the single-cell data, with TEAD3 being predominantly expressed in tumor cells." (PMID 41034991, 2025). "Studies have shown that ADH5 and ADH7 may play an anti-tumor role in the carcinogenesis of Non-small cell lung cancer (NSCLC) and can be used as biomarkers to predict NSCLC patients." (PMID 36387908, 2022).
infection (1 paper, 2021). The state of being infected such as from the introduction of a foreign agent such as serum, vaccine, antigenic substance or organism. "Genes uniquely triggered by M. riyadhense infection compared with other mycobacteria included Cd22, Gpr65, Adh7 and TrnT; however, no functional categories were statistically enriched from this category of genes." (PMID 34396095, 2021).
ADH7 also shares sentences with these, for which no sentence is quoted: adenocarcinoma (2 papers); alcoholism (1); colorectal cancer (1); corneal degeneration (1); esophageal adenocarcinoma (1); esophageal squamous cell carcinoma (1); gastric adenocarcinoma (1); head and neck squamous cell carcinoma (1); malaria (1); myocardial infarction (1); oesophageal cancers (1); oral cavity cancer (1); pterygium (1); vitiligo (1).